Y_RNA (Y RNA )
Gene: Miscellaneous RNA gene on chromosome 18 (24,429,505 to 24,429,609, forward strand). Ensembl gene ENSG00000199636.
Homologues: Orthologues: chimpanzee Y_RNA (100% identical). Paralogues in human: Y_RNA (79% identical), Y_RNA (78% identical), Y_RNA (77% identical), RNY3 (76% identical), Y_RNA (76% identical), Y_RNA (75% identical), RNY3P1 (74% identical), RNY3P4 (74% identical), Y_RNA (74% identical), RNY3P14 (73% identical), RNY3P16 (73% identical), Y_RNA (73% identical), and 90 more.